PRKN (parkin RBR E3 ubiquitin protein ligase)
Diseases named in the same sentence as PRKN in open-access papers (continued):
Sharing a sentence is not in itself a finding about the gene and the disease.
tumor (continued). "In this study, we have shown that reexpression of PRKN in genetically disparate tumor types transcriptionally activates a potent IFN response." (PMID 39213189, 2024). "For instance, PRKN expression is undetectable in virtually all examined human cancers and tumor cell lines, suggesting a general role in tumor suppression." (PMID 39213189, 2024). "Together with other findings that PRKN is required for efficient tumor antigen presentation and response to immunotherapy, these data identify PRKN as a therapeutically actionable, multifunctional mediator of antitumor immunity." (PMID 39213189, 2024). "First, and consistent with recent findings, endogenous PRKN mRNA levels were mostly undetectable in a large panel of human and murine tumor cell lines." (PMID 39213189, 2024). "However, different from these molecules, which are genetically lost in cancer, PRKN epigenetic silencing in tumors is reversible by clinically approved demethylating therapy, which restores endogenous PRKN levels in the tumor microenvironment and associated IFN signaling." (PMID 39213189, 2024). "Differently from this model, however, reexpression of PRKN in tumor cell types (left) increased the levels of TRIM30-α mRNA (right)." (PMID 39213189, 2024). "RT-qPCR and Western blot analyses revealed that, compared to the sh-NC group, the sh-SIRT1 group had significantly lower expressions of BNIP3, PINK1, and PRKN and their corresponding proteins in the tumor tissues." (PMID 39266959, 2024). "More particularly, elimination of defective mitochondria and tumor suppression are mediated via the PINK1/PARK2 pathway, in which PRKN/PARK2 is transformed into E3 ligase that ubiquitinates the impaired mitochondrial proteins." (PMID 36833401, 2023). "Sorafenib significantly upregulated the protein levels of PINK1 and PRKN in tumor tissues, while OA strongly reduced these levels." (PMID 37670307, 2023). "The 1° tumor had eight variants in MKI67, PRKN, PCLO, POLE, CDKN1C, IGSF3, and MED12 genes, which were also present in the brain and spine metastatic cell lines but not present in the parental cell line." (PMID 36900209, 2023). "Similar to PINK1/PRKN deficiency in PD, while defect in melatonin may be detrimental in the setting of chronic neuroinflammation, downregulating melatonin may be beneficial in activating innate immune response in the context of tumor-mediated immune suppression." (PMID 33520994, 2020). "Biological studies demonstrate that PRKN possesses both prosurvival and growth suppressive capacities and its function as a tumor promoter or suppressor is highly dependent on cancer subtype and context." (PMID 33456497, 2020). "In summary since PRKN and the mitophagy process play a pivotal role in neurodegeneration and tumor progression, our findings identify in miR-218 a potential therapeutic target for counteracting neurodegenerative and cancer diseases." (PMID 31948106, 2020). "This suggests a potential role of USP14 and BAG4 in promoting tumor progression, while PRKN may act as a tumor suppressor in CRC (MSI-H)." (PMID 40316942, 2025). "The significant clinical relevance of USP14, BAG4, and PRKN are proved in tumor tissues." (PMID 40316942, 2025). "Additionally, western blot analysis revealed that PRKN levels in tumor cells were lower than those in normal pancreatic epithelial cells." (PMID 39836601, 2025). "Mutations in PRKN and PINK1, for instance, may disrupt their tumor-suppressive functions, leading to an enhanced survival mechanism in cancer cells, making them more resistant to treatment." (PMID 39859167, 2025). "Evidence further supports PRKN as a critical tumor-suppressor factor in cancer development." (PMID 41300754, 2025). "On the other hand, it is clear that other mechanisms also participate in PRKN tumor suppression." (PMID 39213189, 2024). "We next looked at the impact of PRKN immune modulation on tumor growth in vivo." (PMID 39213189, 2024).
tumor (continued). "Hence, more work is needed to determine the contributions of mitophagy and HIF-1α stability to PRKN’s tumor suppressor function." (PMID 37190124, 2023). "The role of PRKN in cancer, as a tumor suppressor gene, has been previously discussed." (PMID 36499697, 2022). "To date, evidence indicated that PRKN is a tumor suppressor." (PMID 36120545, 2022). "Additionally, we observed 35 intra-chromosomal SVs within the African-derived PRKN-PACRG positive tumour N0081." (PMID 36045381, 2022). "Two neighboring genes in this region, QKI and PRKN have been appointed as tumor suppressors in GBM." (PMID 36051438, 2022). "But how PRKN behaves in tumor progression especially in HNSCC is still indefinite." (PMID 33456497, 2020). "We next investigated whether PRKN could block HACD2‐mediated tumor growth." (PMID 39836601, 2025). "Consistent with the in vitro results, PRKN overexpression similarly blocked HACD2‐induced proliferation of subcutaneously transplanted tumors, and the increase in lactate levels caused by HACD2 overexpression in tumor tissues was also alleviated by PRKN overexpression." (PMID 39836601, 2025). "Further analysis across different tumor grades demonstrated a clear association between protein expression and disease severity: USP14 and BAG4 levels increased progressively with higher tumor grades, while PRKN expression decreased as the tumor grade advanced." (PMID 40316942, 2025). "Next, we asked whether PRKN IFN gene expression was a general property of disparate tumor types." (PMID 39213189, 2024). "On this basis, epigenetic therapy may be a suitable approach to reawaken PRKN dual tumor suppression in the clinic, reinvigorating effector T cell functions in the microenvironment (this study) and tumor antigen presentation, while concomitantly inhibiting tumor cell metabolism and invasion." (PMID 39213189, 2024). "We began this study by asking whether reexpression of PRKN in tumor cells affected gene expression." (PMID 39213189, 2024). "Finally, we asked whether the pathway of PRKN immune modulation was restricted to the tumor microenvironment." (PMID 39213189, 2024). "Another study focused on Parkin RBR E3 ubiquitin protein ligase (PRKN or PARK2), an E3 ubiquitin ligase with a known tumor-suppressing role and its interaction with ELK1." (PMID 40862737, 2025). "Mechanistically, siRNA silencing of HMGB1 abolished PRKN IFN gene expression in human (PC3) and murine (TRAMP-C2) tumor cell types." (PMID 39213189, 2024). "We observed that PRKN expression depleted the cellular content of the alarmin and potent DAMP, High Mobility Group Box 1 (HMGB1) in multiple tumor cell types, compared with control cultures." (PMID 39213189, 2024). "Second, treatment with decitabine, which induces demethylation of the PARK2 promoter and reexpression of endogenous PRKN in tumor cells, also induced HMGB1 release in the CM of multiple tumor types." (PMID 39213189, 2024). "To further elucidate the molecular mechanism underlying the effect of ailanthone against HCC in vivo, we performed IHC analysis to investigate the protein expression of LC3, PINK1, PRKN, BAX, and BAK1 in tumour tissues." (PMID 39723259, 2024). "PRKN-induced CD8+ T cells selectively accumulated in the microenvironment and inhibited transgenic and syngeneic tumor growth in vivo." (PMID 39213189, 2024). "In HepG2-derived xenograft model and a PDX model of HCC, CDK9 inhibitor, PHA767491 and oroxylin A (OA) from Scutellaria baicalensis significantly decreased the protein expression of CDK9, PINK1, PRKN, p-SIRT1, FOXO3 and BNIP3 in tumor tissues." (PMID 37670307, 2023). "Three neighboring genes residing this locus are PRKN (PARKIN), PACRG (Parkin Coregulated Gene), and QKI (QUAKING), and both PRKN and QKI have been shown to be tumor suppressors in GBM." (PMID 36051438, 2022). "We observed a decreasing expression level of HSPB8 and PRKN and an increasing expression level of EGFR, CDKN2A, FADD, and ITGA3 in tumor samples." (PMID 33456497, 2020).
tumor (continued). "The study highlights the USP14/BAG4/PRKN axis as a critical pathway in CRC (MSI-H), suggesting that targeting USP14 could inhibit tumor progression and improve chemotherapeutic outcomes." (PMID 40316942, 2025). "We hypothesize that USP14 regulates tumor growth and response to chemotherapy through interactions with BAG4 and PRKN, thereby influencing mitophagy and apoptosis pathways." (PMID 40316942, 2025). "The role of PRKN in reinvigorating an antitumor immune microenvironment via IFN signaling and effector/cytotoxic CD8+ T cell activation (this study) adds to these pathways and defines a unique pathway of dual mode tumor suppression." (PMID 39213189, 2024). "Although an IFN response in cancer is contextual and may trigger pro-or antitumorigenic responses, PRKN IFN signaling delivered potent anticancer activity, inhibiting transgenic and syngeneic tumor growth in vivo." (PMID 39213189, 2024). "Although undetectable in most malignancies, consistent with a general role in tumor suppression, the mechanism(s) of deregulated PRKN expression in cancer have not been clearly delineated." (PMID 39213189, 2024). "Consistent with tumor suppression, effectors of tumorigenesis (Myc, Myb, NKX2-3, and TRIM24), metastasis (NFE2L2), oncogenic transformation (FOXM1), and cell cycle (E2F2 and E2F3) were also inhibited in the presence of PRKN." (PMID 39213189, 2024). "In addition, in a KRAS-driven tumor model, the depletion of PINK1 or PRKN promotes pancreatic tumorigenesis in mice." (PMID 33262988, 2020). "In TRAMP mice, endogenous PRKN is expressed in the prostate at 10 weeks of age, reduced, albeit still detectable, at 26 weeks, and entirely lost by 40 weeks, consistent with the absence of PRKN in advanced tumors and tumor cell lines." (PMID 39213189, 2024). "While these responses were independent of mitophagy, a role of PRKN innate immunity in cancer is unknown and a potential link of this pathway to tumor suppression has not been considered." (PMID 39213189, 2024). "In addition, PRKN immune modulation was specific for tumor-bearing mice because PRKN-KO mice showed no significant changes in lymphoid or myeloid splenocytes at 26 weeks of age compared with WT C57BL/6J mice." (PMID 39213189, 2024). "Previous study found impaired PINK1 and PRKN expression could promote the degradation of SLC25A37 and SLC25A28 and increase the mitochondrial iron accumulation, which lead to AIM2-mediated HMGB1 release that further induced expression of CD274/PD-L1 in tumor cells." (PMID 36612054, 2022). "Immunohistochemical staining of tumor tissues from clinical patients with PC verified the negative correlation between HACD2 and PRKN expression." (PMID 39836601, 2025).
cancer (109 papers, 2010 to 2026). A tumor composed of atypical neoplastic, often pleomorphic cells that invade other tissues. "Three different cancer types appeared in one particular PRKN-carrier PD patient, which again highlights the high risk of cancer in PRKN carriers." (PMID 41300754, 2025). "PRKN deficiency has been observed in several cancer phenotypes in humans, including colorectal cancer, glioblastoma, melanoma, lung cancer, and breast cancer." (PMID 38255314, 2024). "The loss of PRKN at both the DNA copy number and mRNA expression levels contributes to cancer progression via redox-mediated inactivation of phosphatase and tensin homolog (PTEN)." (PMID 31921812, 2019). "Interestingly, 3 (18.75%) out of 16 PRKN mutation carriers with PD had a positive cancer history, which aligns with previous data of an increased risk of cancer in these patients." (PMID 41300754, 2025). "Additionally, loss or down-regulation of PRKN has been associated with various types of cancer, and its loss has been shown to result in a switch to aerobic glycolysis, known as the Warburg effect, which is a characteristic of many cancer types." (PMID 34354738, 2021). "Moreover, PRKN/PARK2 loci have been related to an overall increased risk of cancer." (PMID 41300754, 2025). "Therefore, PRKN deficiency contributes to the Warburg effect in cancer." (PMID 38255314, 2024). "Some genes, such as LRRK2 and PRKN, may be associated with both cancer and PD." (PMID 32733355, 2020). "Targeting the USP14/BAG4/PRKN axis to enhance mitophagy shows promise for improving cancer treatment efficacy." (PMID 40316942, 2025). "We then explored the methylation levels (beta-values, HumanMethylation450) of MAP1LC3A, OPTN, PINK1, PRKN, SRC, BNIP3L, and BECN1 in pan-cancer and their association with gene expression and the immune cell infiltrates." (PMID 39859167, 2025). "Studies on PRKN in the context of cancer have demonstrated that PRKN regulates the degradation of cyclins and cyclin-dependent kinases involved in the G1/S transition, the loss of which promotes unchecked proliferation." (PMID 38979135, 2025). "The study underscores the therapeutic promise of targeting the USP14/BAG4/PRKN axis to boost mitophagy and increase cancer cell sensitivity to chemotherapy, especially oxaliplatin." (PMID 40316942, 2025). "The distinctive contribution of this study lies in its examination of genetic forms of PD—including carriers of LRRK2, GBA1, SNCA, PRKN, and PINK1 mutations—in relation to cancer risk." (PMID 41300754, 2025). "Significant changes in mRNA expression levels were identified across eight cancer types, with PRKN and PINK1 being generally downregulated and SRC being upregulated." (PMID 39859167, 2025). "These tumor-suppressive actions of Parkin are consistent with the genetic and epigenetic inactivation of the PRKN gene found in a variety of human cancers." (PMID 40687836, 2025). "Our findings indicate that the expression levels of CSNK2B, MTERF3, and PGAM5 are elevated in multiple cancers, while the expression levels of PINK1 and PRKN are reduced in several cancers." (PMID 38913914, 2024). "ARIH1 induce mitophagy in a PRKN-independent manner in cancer cells resulting in cancer cell resistance to anti-cancer therapy." (PMID 37007026, 2023). "PRKN is located at chromosome 6q25.2-27, a large genomic region that is frequently compromised in various cancers 3-6." (PMID 34815803, 2021). "A similar pattern of restricted expression is also observed for the other antisense TSSs: PRKN-int3AS and PRKN-int4AS in cancer cell lines, PARKN-int5AS in ARPE-19 EMT cells induced with TGFβ and TNFα, and PARKN-3′AS1 in CD14+ monocytes." (PMID 30610612, 2019). "Among these genes, NGFR, PRKN, STAT3, IDH2, etc. were associated with the neuronal system and cancer pathway as the significant terms (P < 0.001)." (PMID 31708732, 2019). "For instance, phosphorylation at S43/S45, as reported in cancer cells, might antagonize PRKN‐mediated degradation." (PMID 41457744, 2026).
cancer (continued). "Targeting mitophagy-related genes like PINK1 and PRKN could potentially sensitize cancer cells to treatment by promoting the accumulation of dysfunctional mitochondria, thereby increasing oxidative stress and cell death." (PMID 39859167, 2025). "Notably, PRKN exhibited the highest alteration frequency, affecting 34% of all cancer samples, followed by OPTN (21%), PINK1 (18%), SRC (15%), BECN1 (13%), MAP1LC3A (9%), and BNIP3L (5%)." (PMID 39859167, 2025). "For example, targeting PINK1 and PRKN to inhibit mitophagy could sensitize cancer cells to treatment by promoting the accumulation of dysfunctional mitochondria and enhancing oxidative stress." (PMID 39859167, 2025). "Next, we studied the mechanism(s) of PRKN induction of IFN signaling in cancer." (PMID 39213189, 2024). "In previous studies, PRKN loss in cancer was not accompanied by increased mutagenesis of the PARK2 gene or copy number alterations." (PMID 39213189, 2024). "Interaction with the mentioned proteins might destabilise AKT1, MDM2, and PRKN signalling pathways, which control cancer cells’ survival, proliferation, invasion, apoptosis, and angiogenesis, making the combined drug’s therapeutic effect promising." (PMID 39204341, 2024). "At variance with this model, we found that reexpression of PRKN in cancer does not cause mitophagy or other hallmarks of mitochondrial dysfunction and potently activates, rather than inhibits, innate immunity through DAMP-regulated IFN signaling." (PMID 39213189, 2024). "Importantly, PRKN antitumor immunity was therapeutically actionable, and a clinically approved demethylating therapy with decitabine restored epigenetically silenced endogenous PRKN expression in cancer and enabled HMGB1-dependent IFN gene expression." (PMID 39213189, 2024). "Furthermore, PRKN was also found to be expressed at low levels in carcinoma tissues in three different BLCA datasets." (PMID 38424181, 2024). "Besides alterations in these cancer hallmark genes, SNVs were identified in the less characterized genes GRM3, MST1R, PRKN, and PIK3C2G." (PMID 34399808, 2021). "Here we expand on our recent findings that loss of parkin RBR E3 ubiquitin protein ligase (PRKN, best known as PARK2)—which is genetically linked to PD—promotes cancer progression via redox-mediated inactivation of phosphatase and tensin homolog (PTEN) by S-nitrosylation." (PMID 29209642, 2017). "Our observation that the PARK2 promoter is heavily methylated in certain tumors in vivo, correlating with worse patient outcome, points to epigenetic silencing as one of the mechanisms for PRKN loss in cancer, compounding other examples of genetic inactivation." (PMID 39213189, 2024). "Overall, the Spearman’s correlation coefficients varied across different cancer types, revealing distinct patterns of immune cell correlation with the expression of OPTN, PINK1, MAP1LC3A, PRKN, BNIP3L, BECN1, and SRC." (PMID 39859167, 2025). "The analysis of CNVs in PRKN, OPTN, PINK1, SRC, BNIP3L, BECN1, and MAP1LC3A across various cancer types revealed significant heterogeneity in the types and frequencies of CNVs." (PMID 39859167, 2025). "We delved into the molecular mechanisms by which LC3, PINK1, PRKN, SRC, BNIP3L, BECN1, and OPTN regulate mitophagy, cancer progression and drug sensitivity or resistance." (PMID 39859167, 2025). "Heterozygous deletions were prevalent in PRKN, BNIP3L, OPTN, and PINK1, particularly in cancers such as LUSC, ESCA, HNSC, and COAD." (PMID 39859167, 2025). "Here, PRKN-induced release of mtDNA in the cytosol, a potent DAMP and major cGAS/STING activator, was insufficient to recapitulate an IFN response in cancer." (PMID 39213189, 2024). "Majority of the NRGs were deregulated in cancer tissues as compared to normal tissues which showed a uniform downregulated expression pattern except for NDRG2, BCL2, PRKN, TLR3, and STUB1." (PMID 36389725, 2022).
cancer (continued). "Last, we gathered the IC50s of a wide variety of drugs among different cancer cell lines through the GDSC and CTRP databases and assessed the relationship between the mRNA values of MAP1LC3A, OPTN, SRC, BNIP3L, BECN1, PINK1, and PRKN and drug sensitivity." (PMID 39859167, 2025). "Here, we conduct a comprehensive analysis of a mitophagy-related gene signature, composed of PRKN, PINK1, MAP1LC3A, SRC, BNIP3L, BECN1, and OPTN, across various cancer types, revealing significant differential expression patterns associated with molecular subtypes, stages, and patient outcomes." (PMID 39859167, 2025). "Overall, these findings highlight the complex landscape of CNVs in PRKN, OPTN, PINK1, SRC, BECN1, BNIP3L, and MAP1LC3A across different cancer types, emphasizing the potential impact of these genetic alterations on cancer pathogenesis and the importance of considering CNVs in therapeutic strategies." (PMID 39859167, 2025). "Notably, genes within common fragile sites, such as PRKN and MACROD2, which are among the top 10 scoring genes, showed an exorbitant impact in metastasized CRC, highlighting their potential relevance in cancer." (PMID 39230704, 2024). "However, we found that PRKN and BAX protein were only slightly upregulated in cancer tissues." (PMID 32649310, 2020).